CDK9 (cyclin dependent kinase 9)
Diseases named in the same sentence as CDK9 in open-access papers (continued):
Sharing a sentence is not in itself a finding about the gene and the disease.
glioblastoma (8 papers, 2014 to 2026). The most malignant astrocytic tumor (WHO grade IV). "Knockdown of CDK9 or selective CDK9 inhibitors reduced YTHDF2 expression levels in glioblastoma stem cells, consistent with our findings." (PMID 38637831, 2024). "In this section, we review studies in glioblastoma and other cancer types that demonstrate how CDK9 inhibition can modulate various cancer cell survival pathways to facilitate an anti-tumor response." (PMID 34207158, 2021). "This review assesses the mechanisms by which CDK9 inhibition impacts cancer cell survival pathways in glioblastoma and other cancer types and presents results from clinical trials involving CDK9 inhibitors." (PMID 34207158, 2021). "Targeting cyclin-dependent kinase 9 (CDK9) is an emerging therapeutic approach that has the potential to overcome the challenges in glioblastoma management." (PMID 34207158, 2021). "Since HK2 and PKM2 promote tumor growth and GSC self-renewal and glioblastomas are heavily reliant on glycolysis for energy production, targeting CDK9 provides a novel mechanism to exploit these metabolic vulnerabilities." (PMID 34207158, 2021). "We had previously reported differential effects on gene expression in human glioblastoma T98G cells when CDK9 activity was either inhibited pharmacologically with FVP or with a dominant negative form of CDK9 (dnCDK9) expressed from an adenoviral vector." (PMID 24886624, 2014). "YY1 also interacts with CDK9 in glioblastoma stem cells and maintains stemness." (PMID 40867514, 2025). "Since BRCA1 is dependent on CDK9 for HR repair, CDK9 inhibition may provide a synthetic lethal mechanism to render glioblastomas more vulnerable to PARP inhibitors." (PMID 34207158, 2021). "In this review, we discuss how targeting CDK9 may help overcome the challenges in treating glioblastomas by modulating not only transcription but also tumor cell metabolism, DNA damage repair, epigenetics, and the immune response." (PMID 34207158, 2021). "Targeting CDK9 has also been shown to induce metabolic stress in glioblastomas." (PMID 34207158, 2021). "A more thorough understanding of these mechanisms may lead to novel combination treatment strategies involving CDK9 inhibitors that can ultimately improve clinical outcomes for glioblastoma patients." (PMID 34207158, 2021). "Moreover, we discuss small-molecule inhibitors of CDK9 in clinical trials and future perspectives on the use of CDK9 inhibitors in treating patients with glioblastoma." (PMID 34207158, 2021). "Targeting CDK9 may thus provide a mechanism to reactivate TSGs in glioblastomas and to counteract hypermethylation of factors that could render the tumor resistant to future treatments." (PMID 34207158, 2021). "The findings from this study may provide a promising CDK9-based strategy to counteract the pro-tumor effects of iASPP-SV in glioblastomas as well." (PMID 34207158, 2021). "Furthermore, since targeting CDK9 resulted in mitochondrial damage, glioblastoma cells are limited in their ability to compensate for energy production via oxidative phosphorylation." (PMID 34207158, 2021). "As part of precision medicine, it will also be necessary to identify specific biomarkers in glioblastoma that can predict treatment response or resistance to CDK9 inhibition, and once determined, these biomarkers can be used to identify subsets of patients that will benefit most from the treatment." (PMID 34207158, 2021). "Furthermore, overexpression of a constitutively active CDK9 mutant rescued glioblastoma cells from zotiraciclib-induced cell death." (PMID 34207158, 2021). "Furthermore, we discuss small-molecule inhibitors of CDK9 that have been or are currently being tested in clinical trials and future directions of targeting CDK9 for the management of glioblastoma." (PMID 34207158, 2021).
glioblastoma (continued). "A previous gene expression profiling study performed with human glioblastoma T98G cells in which CDK9 activity was inhibited either with a dominant negative mutant form of CDK9 (dnCDK9) or the pharmacological inhibitor Flavopiridol unveiled striking differences in gene expression effects." (PMID 24886624, 2014). "Targeting CDK9 may thus provide a mechanism to reduce HOTAIR expression in glioblastomas as well." (PMID 34207158, 2021). "In this study we sought to compare global changes in gene expression resulting from inhibition of CDK9 activity by different means in hTERT immortalized normal human fibroblasts and primary astrocytes, as well as compare them to previous data obtained using T98G glioblastoma cells." (PMID 24886624, 2014). "Subsequent Co-IP experiments in glioblastoma cell lines confirmed the interaction between PRMT6 and CDK9." (PMID 38637831, 2024). "This provides yet another reason for the combined use of CDK9 and BRD4 inhibitors to synergistically inhibit proliferation of glioblastoma cells." (PMID 34207158, 2021). "Here we find that glioblastoma stem cells (GSCs) are selectively sensitive to CDK12/CDK13 inhibition, whereas CDK7 and CDK9 inhibition cause non-specific cytotoxicity." (PMID 41882177, 2026). "Inhibition of cyclin-dependent kinase 9 (CDK9) can impact multiple survival pathways in cancers and may be a promising therapeutic approach for glioblastoma, which is known to be highly resistant to treatments and thus challenging to treat." (PMID 34207158, 2021). "In glioblastomas, CDK9 was also found to be highly expressed compared to non-tumor-containing brain samples." (PMID 34207158, 2021). "Moreover, in patients with non-CpG island methylator phenotype (a subset of glioblastoma patients with poor survival outcomes), higher expression of CDK9 was found to correlate with worse clinical prognosis." (PMID 34207158, 2021).
sarcoma (8 papers, 2020 to 2026). A usually aggressive malignant neoplasm of the soft tissue or bone. "It has been demonstrated that inhibiting CDK9 in sarcoma lowers the expression of these oncogenes as well as the development and proliferation of various sarcoma cells." (PMID 40361480, 2025). "Based on its central role in transcriptional initiation and elongation, CDK9 quickly came into focus to consider its contribution to tumor development and progression, also in pediatric sarcoma." (PMID 32012890, 2020). "Clinical trials of natural products targeting CDK9 used as single agents or in combination in solid tumor including sarcomas." (PMID 32903585, 2020). "In addition, inhibiting CDK9 in sarcomas has been shown to downregulate the expression of some oncogenes and reduce the proliferation and growth of various sarcoma cells." (PMID 40492119, 2025). "Furthermore, as many CDK9 inhibitors are under active clinical development primarily for hematologic malignancies or extracranial sarcomas, few compounds have robust data available on effective penetration across the blood brain barrier." (PMID 38816355, 2024). "CDK9 is widely expressed in different pediatric sarcomas and other pediatric and adult tumor entities, while the local tumor site in EwS may influence its level of expression." (PMID 32012890, 2020). "To leverage this dependency for targeted eradication of pediatric sarcomas with MDM2 overexpression, we develop MDM2-recruiting proteolysis-targeting chimeras that selectively degrade the CDK9/Cyclin T complex (P-TEFb)." (PMID 42318649, 2026). "It has been noted that CDK9 overexpression and activation result in the production of oncogenes, such as MYC and MCL-1, which promote the growth and spread of sarcoma." (PMID 40361480, 2025). "As BRD4 interacts with Cyclin-dependent Kinase 9 (CDK9) in other fusion-driven sarcomas, combinatorial treatment with BRD4 and CDK9 inhibitors may exert synergistic anti-tumor effects in PF+ RMS." (PMID 37345159, 2023). "Interestingly, the drug AT-7519, also a CDK-9 inhibitor, has not been considered in sarcoma while it is already undergoing clinical trials as an anticancer drug in different cancer types." (PMID 35580047, 2022).
cervical cancer (7 papers, 2020 to 2022). A primary or metastatic malignant neoplasm involving the cervix. "As a result, loss of caspase-8 may lead to the hyperactivated state of CDK9, altering the transcriptional landscape of cervical cancer towards a more aggressive phenotype." (PMID 36428594, 2022). "To further elucidate the underlying mechanism of ASF1B and CDK9 in cervical cancer progression, we hypothesized that ASF1B knockdown reduces CDK9 protein levels by promoting its degradation." (PMID 32848135, 2020). "This renders CDK9 a promising molecular target for treating cervical cancer patients with low Caspase-8 expression." (PMID 36399280, 2022). "Ultimately, our recent translational investigations have revealed that caspase-8 knockout cancer cells and cervical cancer lines are more resistant to the small-molecule CDK9 inhibitor BAY1251152 in both 2D and 3D spheroid culture conditions." (PMID 36428594, 2022). "We have, thus far, demonstrated that low Caspase-8 expression in cervical cancer cell lines and primary tumors leads to higher CDK9 kinase activity." (PMID 36399280, 2022). "Here, we report a significant association between disease-related outcomes and pretreatment levels of caspase-8, CDK9 and pCDK9 (Thr 186) expression in a cohort of locally advanced cervical cancer patients treated with definitive CRT and BT." (PMID 36428594, 2022). "In conclusion, we believe that the data presented by this study support further pre-clinical and clinical evaluations of CDK9 inhibitors in advanced and resistant cervical cancer." (PMID 36399280, 2022). "In summary, we have confirmed that CDK9 interacts with the p12 domain of Caspase-8 within the nucleus of cervical cancer cells." (PMID 36399280, 2022). "Taken together, these results suggest that impaired expression of ASF1B inhibits cervical cancer growth and induces apoptosis, which is associated with modulation by the ASF1B/CDK9 pathways." (PMID 32848135, 2020). "As several third-generation CDK9 inhibitors such as AZD-4573, BAY1251152 and JSH-150 are currently undergoing clinical trials, our findings emphasize CDK9 as a promising molecular target for treating cervical cancer patients, especially those with low caspase-8 expression." (PMID 36428594, 2022). "However, stringent assessment and stratification of patients with high and low caspase-8 expression levels will be critical to evaluate the clinical success of future CDK9-based targeted strategies in cervical cancer and other tumor entities." (PMID 36428594, 2022). "Similarly, our investigation of a cohort of primary cervical cancer patient-derived tissues also confirmed a significant correlation between high Caspase-8 expression and low CDK9 Thr186 phosphorylation, and low RNAPII Ser2 phosphorylation." (PMID 36399280, 2022). "These experiments demonstrated that the response of cervical cancer to cisplatin-based chemotherapy might be significantly improved by concurrently blocking CDK9." (PMID 36428594, 2022). "In summary, our data support the notion that increased pretreatment tumor levels of caspase-8 and CDK9 predict superior clinical responses in cervical cancer patients treated with definitive CRT plus BT, while higher levels of pCDK9 detection are predictive of an impaired clinical response." (PMID 36428594, 2022). "Work on cervical cancer cell lines revealed that Caspase-8, located in their nuclear fractions, could directly interact with and inhibit the phosphorylation of CDK9 at Thr186." (PMID 36399280, 2022). "In summary, the results of our 2D- and 3D-cellular experiments demonstrated that the response of cervical cancer to Cisplatin-based standard chemotherapy might significantly improve by concurrently blocking CDK9 activity using small-molecule inhibitors." (PMID 36399280, 2022). "Thus, we wondered whether targeting CDK9 would improve the response to Cisplatin-based chemotherapy in Caspase-8 KO cervical cancer cells." (PMID 36399280, 2022).
cervical cancer (continued). "Furthermore, our translational work with the small-molecule CDK9 inhibitor BAY1251152 revealed that combining it with Cisplatin synergistically enhanced the sensitivity of Caspase-8 depleted cervical cancer cells to Cisplatin under both 2D- and 3D-cell culture conditions." (PMID 36399280, 2022). "Crucially, low Caspase-8 expression in cervical cancer patients leads to poor prognosis, higher CDK9 phosphorylation at Thr186, and increased RNAPII activity in cervical cancer cell lines and patient biopsies." (PMID 36399280, 2022). "According to a recent study, ASF1B can promote cervical cancer development by stabilizing CDK9, whereas inhibiting ASF1B can stop cervical cancer from growing by interrupting the cell cycle." (PMID 35875094, 2022). "Subsequently, we further confirmed that ASF1B and CDK9 are the factors of a nuclear complex to promote cervical cancer progression by co-IP and colocalization of ASF1B and CDK9 in the nucleus." (PMID 32848135, 2020). "This suggests that the absence of Caspase-8 expression de-sensitizes cervical cancer cells to CDK9 inhibitors." (PMID 36399280, 2022). "According to the literature, ASF1B interacts with CDK9 in cervical cancer cells, but it has not been reported in liver cancer cells." (PMID 35087760, 2021).
chordoma (7 papers, 2020 to 2024). Chordomas are rare malignant tumors arising from embryonic remnants of the notochord in axial skeleton. "Consistent with our work, we observed CDK9 inhibition to induce a concomitant decrease of Mcl-1 and associated antiapoptotic factors, with an overall suppression of chordoma cell growth." (PMID 31892980, 2020). "Taken together, CDK inhibition (predominantly CDK7 and CDK9 inhibition) is a suitable option for reducing TBXT expression in chordoma cell lines." (PMID 38786326, 2024). "CDK7 and CDK9 were shown to reduce the viability of chordoma cells through a genome-scale CRISPR/Cas9 approach as well as the large-scale testing of >450 small molecules." (PMID 38786326, 2024). "CDK7 and CDK9 inhibition was lately identified as being effective in reducing viability in four chordoma cell lines, most likely due to a reduction in brachyury levels." (PMID 38786326, 2024). "CDK inhibitors (particularly inhibitors of CDK7 and CDK9) have been shown to disrupt the autoregulatory landscape of brachyury, downregulate cellular brachyury levels in a limited number of chordoma cell lines, and reduce tumour growth in vivo." (PMID 38786326, 2024). "Knockdown of AURA, MOK and CDK9 in chordoma cell lines and treatment with CDK9 inhibitor AZD4573 were shown to compromise cell proliferation in functional experiments." (PMID 37197427, 2023). "The knockdown of these kinases markedly suppressed chordoma cell growth, and this was also the case for cells treated with the CDK9 inhibitor AZD4573." (PMID 36248973, 2022). "Given the advantage of this artificial environment, we investigated the effect of CDK9 inhibition on chordoma cell proliferation within the 3D culture." (PMID 31892980, 2020). "Overall, our results support LDC000067 mediated inhibition of CDK9 as a potential strategy in chordoma therapy." (PMID 31892980, 2020). "To evaluate how CDK9 silencing affects CDK9 regulated proteins, we analyzed the expression of RNAP II within CDK9 siRNA transfected chordoma cells." (PMID 31892980, 2020). "After this treatment, MTT revealed CDK9 knockdown to inhibit chordoma cell growth and proliferation." (PMID 31892980, 2020). "To establish the existence of these two isoforms in primary cancer as well, we examined CDK9 expression in eight primary chordoma specimens." (PMID 31892980, 2020). "To expand the clinical application of our work and further characterize the role of CDK9 in chordoma cell growth and proliferation, we conducted an inhibition analysis using the specific CDK9 inhibitor LDC000067." (PMID 31892980, 2020). "Taken together, these data outline how elevated CDK9 expression is a potential prognostic marker and agent of chordoma progression." (PMID 31892980, 2020). "To evaluate the functional role of CDK9 in chordoma, we used synthetic RNA interference (RNAi) to disrupt CDK9 expression in chordoma cells lines." (PMID 31892980, 2020). "CDK9 silencing with siRNA decreased growth and proliferation of chordoma cells and lowered levels of Mcl-1 and RNA polymerase II (RNAP II) phosphorylation." (PMID 31892980, 2020). "Although there is abundant room for further research and validation, these findings suggest CDK9 is a potential therapeutic target for chordoma treatment." (PMID 31892980, 2020). "To evaluate the clinical relevance of CDK9 expression in chordoma, we analyzed its expression in a human chordoma TMA." (PMID 31892980, 2020). "Our study shows the expression of Survivin to decrease and the expression of the pro-apoptotic protein Bax to increase in LDC000067 treated chordoma cells, suggesting this drug can disrupt aberrant CDK9 apoptotic signaling cascades." (PMID 31892980, 2020). "In summary, our study demonstrates that CDK9 is highly expressed in chordoma, and when elevated, correlates with recurrence and worse prognosis." (PMID 31892980, 2020). "Collectively, these results suggest that inhibition of CDK9 suppresses growth and proliferation of chordoma cells." (PMID 31892980, 2020).